CCDC169-SOHLH2 (CCDC169-SOHLH2 readthrough)
Synonyms: C13orf38-SOHLH2
Gene: Protein-coding gene on chromosome 13 (36,168,794 to 36,297,842, reverse strand). Ensembl gene ENSG00000250709.
Genetic constraint (gnomAD): Loss-of-function variants: 37 observed, 67.34 expected, observed/expected ratio (o/e) 0.55, 90% interval 0.42 to 0.72. The upper end of that interval is the gene's LOEUF score, 0.72, which puts it in group 2 of 6, group 1 being the genes least tolerant of losing a copy. Missense variants: 505 observed, 604.01 expected, observed/expected ratio (o/e) 0.84, 90% interval 0.78 to 0.9. Synonymous variants: 209 observed, 220.6 expected, observed/expected ratio (o/e) 0.95, 90% interval 0.85 to 1.06.